RN7SKP224 (RN7SK pseudogene 224)
Gene: Miscellaneous RNA gene on chromosome 2 (48,217,575 to 48,217,899, forward strand). Ensembl gene ENSG00000201010.
Homologues: Orthologues: chimpanzee 7SK (99% identical), guinea pig 7SK (59% identical). Paralogues in human: RN7SKP255 (74% identical), RN7SKP203 (72% identical), RN7SKP22 (72% identical), 7SK (71% identical), RN7SKP71 (71% identical), RN7SKP77 (71% identical), RN7SKP50 (70% identical), RN7SKP90 (70% identical), RN7SKP3 (70% identical), RN7SKP33 (70% identical), RN7SKP47 (70% identical), RN7SKP79 (70% identical), and 284 more.